MOV10 (Mov10 RNA helicase)
Diseases named in the same sentence as MOV10 in open-access papers (continued):
Sharing a sentence is not in itself a finding about the gene and the disease.
Arthritis (1 paper, 2023). Inflammation of a joint. "Similar to anti-RO60, anti-MOV10 were higher in SLE patients with anti-dsDNA antibodies, in those with arthritis, and in those with elevated type I interferons." (PMID 39606792, 2023).
autism spectrum disorder (1 paper, 2023). A spectrum of developmental disorders that includes autism, and Asperger syndrome. "With regards to genes with probes at suggestive significance at school-age (WDR20, MOV10, and TAOK2), these have previously been linked to neurodevelopmental and psychiatric risk, such as autism spectrum disorder (ASD) and schizophrenia." (PMID 36385171, 2023).
breast carcinoma (1 paper, 2020). "Abnormal expression of MOV10 is related to radiotherapy resistance and cell proliferation in breast cancer." (PMID 33001583, 2020).
cervical cancer (1 paper, 2019). A primary or metastatic malignant neoplasm involving the cervix. "And studies have found that mRNA and protein expressions of MOV10 in cancer cells such as cervical cancer are 2 to 3 folds higher than normal cells, which suggesting that MOV10 may be related to the development and progression of tumors." (PMID 30621721, 2019).
COVID-19 (1 paper, 2021). A disease caused by infection with severe acute respiratory syndrome coronavirus 2. "Importantly, both MOV10 and IFNA6 have been reported in patients infected with COVID-19." (PMID 34965855, 2021).
developmental delay (1 paper, 2017). "In fact, CNVs containing Mov10 have been found in individuals with developmental delay." (PMID 28662698, 2017).
herpesvirus infection (1 paper, 2022). "Moloney leukemia virus 10 protein (MOV10) is an interferon (IFN)-inducible RNA helicase implicated in antiviral activity against RNA viruses, yet its role in herpesvirus infection has not been investigated." (PMID 35157734, 2022).
lung carcinoma (1 paper, 2020). "Fortunately, we obtained four hub genes (MAPK3, MOV10, XAB2, and POLR2A), which potentially interact with BCAR1 and play carcinogenetic roles in lung cancer." (PMID 33001583, 2020).
Obesity (1 paper, 2021). Accumulation of substantial excess body fat. "MOV10 and WNK 1 genes were overexpressed both before and after HCT compared with the obesity control group." (PMID 33927307, 2021). "The MOV10 and WNK 1 genes were overexpressed in both pre-HCT and post-HCT group compared with the obesity control group." (PMID 33927307, 2021). "In the post-HCT group we found significantly lower expression of AGTR2, FLJ32810, NR3C2 and TMEM133 genes, and significantly higher expression of BAT2D1, MOV10, PIK3CG and WNK1 genes compared with the obesity control group." (PMID 33927307, 2021). "In the pre-HCT group we found significantly lower expression of AGTR2, BLK, FLJ32810 and TMEM133 genes, and significantly higher expression of MOV10 and WNK1 genes compared with the obesity control group." (PMID 33927307, 2021).
pancreatic cancer (1 paper, 2021). "Moreover, the miR-760/MOV10/ITGB1 pathway was important for the sensitivity of cells to the chemotherapy drugs in pancreatic cancer." (PMID 33456356, 2021).
preeclampsia (1 paper, 2021). Preeclampsia is a hypertensive disorder of pregnancy that is characterized by new-onset hypertension with proteinuria presenting after 20 weeks of gestation, and depending on mild or severe forms may initially present with severe headache, visual disturbances, and hyperreflexia. "There was relationship between MOV10 polymorphism and preeclampsia." (PMID 33269545, 2021).
SLE nephritis (1 paper, 2023). "Anti-MOV10 titers also did not correlate with SLE nephritis, while anti-ORF1p titers did, but instead inversely correlated with photosensitivity (not shown)." (PMID 39606792, 2023).
infection (11 papers, 2010 to 2025). The state of being infected such as from the introduction of a foreign agent such as serum, vaccine, antigenic substance or organism. "HSV-1 strains KOS, F, 17syn+ and Patton all caused comparable increases in Mov10 mRNA levels at an MOI of 5 at 18 hours post-infection (hpi)." (PMID 35157734, 2022). "The results showed that N exhibits remarkable colocalization with MOV10 in cytoplasm upon SFTSV infection, further confirming the association of N with MOV10." (PMID 33284835, 2020). "Together, these results suggested that antiviral activity of MOV10 may occur only after infection with highly pathogenic CoVs." (PMID 34517762, 2021). "Similarly, both GTV and HRTV caused significant induction of MOV10 from early stages of infection as well." (PMID 33284835, 2020). "Meanwhile Mov10 mRNA was significantly upregulated at 3, 6 and 10 dpi in these TG, with average levels being 1 to 1.5 logs (>10-fold) higher than mock infection." (PMID 35157734, 2022). "At 28 dpi, Mov10 mRNA returned to levels that were slightly yet still significantly higher than mock infection, suggesting that while MOV10 upregulation was driven by acute infection, it lasted beyond the acute phase." (PMID 35157734, 2022). "Overexpression of MOV10 was confirmed by western blotting after infection of Neuro-2a cells with these recombinant viruses." (PMID 35157734, 2022). "Here we show that during HSV-1 acute infection Moloney leukemia virus 10 protein (MOV10) was induced to restrict HSV-1 productive infection." (PMID 35157734, 2022). "It was shown that SFTSV infection specifically upregulates MOV10 expression in vitro and that MOV10 inhibits the replication of SFTSV and other related viruses (Heartland virus (HRTV) and Guertu virus (GTV)) in infected cells." (PMID 33925004, 2021). "Ectopic expression of Mov10 diminishes per-particle infectivity resulting in virus impaired at an early step of infection in target cells." (PMID 20140200, 2010). "Moreover, animal infection experiments with MOV10 knockdown corroborated the role of MOV10 in restricting SFTSV infection and pathogenicity in vivo." (PMID 33284835, 2020). "In addition, the number of studies is increasing that confirm MOV10 not only has important roles in infection by human viruses, such as HIV and human hepatitis delta virus, but also shows antiviral activity against animal RNA viruses." (PMID 33195554, 2020). "Furthermore, we found that HIV-1 produced in the presence of high levels of Mov10 is restricted in infection of target cells either prior to or at the initiation of reverse transcription." (PMID 20140200, 2010). "Following transfection of Neuro-2a cells with MOV10 and infection with KOS, we immunoprecipitated MOV10 and then analyzed the interacting proteome by liquid chromatography (LC)-mass spectrometry (MS)/MS." (PMID 35157734, 2022). "Depletion of the RNAi pathway proteins Dicer, MOV10, TRBP2 and Matrin 3 decreased viral load in infected cells, alluding to an impact of the RNAi pathway in the establishment of a productive infection." (PMID 35893693, 2022). "Further, the strong interaction of SFTSV N with endogenous MOV10 was also confirmed by additional pulldown and Co-IP experiments in the contexts of transfection or SFTSV infection, respectively." (PMID 33284835, 2020). "We investigated the effect of MOV10 down-regulation and MOV10 over-expression on HBV in a variety of cell lines, as well as in an infection system using a replication competent virus." (PMID 31319455, 2019). "However, the role that MOV10 has on HBV replication in an infection system is unknown." (PMID 31319455, 2019). "Moreover, our study highlights the coordinated response of host restriction factors, such as MOV-10 and APOBEC-3, in mitigating L1 activity, underscoring the complex interplay between retroelement regulation and immune homeostasis during Tc infection." (PMID 40429613, 2025).
infection (continued). "In Raw264.7 cells, MOV10 protein was upregulated only slightly during infection, and in HFF cells, no upregulation was observed." (PMID 35157734, 2022). "Moreover, we found that although MOV10 is a weak ISG, it can be significantly and specifically induced in response to infections of SFTSV and related bunyaviruses, likely serving as an add-on to the anti-bunyavirus function of MOV10." (PMID 33284835, 2020). "However, to our knowledge, the role of MOV10 in infection with herpesviruses, including HSV, has not been investigated." (PMID 35157734, 2022). "However, by contrast, infection of Sendai virus (SeV, a model RNA virus) that resulted in dramatic upregulation of the typical ISGs did not evidently affect MOV10 expression, reflecting the specific induction of MOV10 by the bunyaviruses." (PMID 33284835, 2020). "However, the role of MOV10 in other cell lines, and more importantly, in the more biologically relevant system of authentic infection by fully infectious viruses, was not addressed." (PMID 31319455, 2019).
cancer (10 papers, 2015 to 2025). A tumor composed of atypical neoplastic, often pleomorphic cells that invade other tissues. "circHIPK3 contains multiple sites for the same RBPs (e.g., DDX54, EIF4A3, FMR1, IGF2BP1, IGF2BP2, LIN28B and MOV10), many of which are involved in chemoresistance and organelle-like structures, such as Cajal body and P-body which are associated with cancer." (PMID 40061896, 2025). "While evidence of the role of MOV10 in cancer and/or the viral mimicry response is scant, some studies have shown that MOV10 participates in tumor emergence and progression." (PMID 35602594, 2022). "However, specific roles for ZAP and MOV10 restriction factors in cancer development and drug resistance have yet to be defined." (PMID 35602594, 2022). "DCAF12 is mainly nuclear in human cancer cells, while MOV10 is dominantly cytoplasmic." (PMID 34065512, 2021). "However, we observed a decrease in MOV10 co-precipitated with SF-DCAF12ΔNLSs in several cancer cell lines." (PMID 34065512, 2021). "We also identified a number of plausible targets that were not previously implicated in cancer, such as MOV10." (PMID 34662337, 2021). "Next, we investigated whether DCAF12 mediates MOV10 degradation in cancer cells." (PMID 34065512, 2021). "Finally, tumors that express low levels of Mov10 express higher levels of FASN, providing correlative evidence for Mov10-regulated lipid metabolism in cancer." (PMID 26029828, 2015). "In addition, the data indicate that NF90 and MOV10 may compete for the binding of common target mRNAs, suggesting a role for NF90 in the regulation of RISC-mediated silencing by stabilizing target mRNAs, such as VEGF, during cancer-induced hypoxia." (PMID 36050755, 2022). "The different subcellular localization of DCAF12 and MOV10 in human cancer cells might explain why we could not reliably observe an increased MOV10 protein level and stability after DCAF12 depletion using small inhibitory (si) RNA or in DCAF12 KO HCT116 cells (data not shown)." (PMID 34065512, 2021).
tumor (4 papers, 2015 to 2022). "Particularly for P4, the shared mutations included several important tumor metastasis–related and drug-resistance genes, such as ZNF143, MUC16, NUMA1, ADAMTS2, and MOV10." (PMID 34616428, 2021). "Some of these tumor samples contained both high- and low-Mov10-expressing regions and the levels of FASN staining in each region was the inverse of the level of Mov10." (PMID 26029828, 2015). "The tissue arrays did not contain sufficient stage III and IV tumor samples to correlate expression of Mov10 and FASN with tumor stage." (PMID 26029828, 2015).
MOV10 also shares sentences with these, for which no sentence is quoted: HIV-1 infection (2 papers); autism (1); benign tumors (1); Fever (1); fragile X syndrome (1); Hepatitis (1); liver dysfunction (1); neurological disorders (1); peripheral nerve lesion (1); Pheochromocytoma and Paraganglioma (1); schizophrenia (1).